CD82 (CD82 molecule)
Diseases named in the same sentence as CD82 in open-access papers (continued):
Sharing a sentence is not in itself a finding about the gene and the disease.
prostate carcinoma (continued). "Malignant tissue sections of prostate cancer displayed significantly decreased expression levels of CD82 and E-cadherin as compared with the corresponding non-neoplastic sections." (PMID 27926483, 2017). "The gene expression analysis with and without CD82 in microarray technique reveals the key role of KA11 in regulating prostate cancer and could be an effective biomarker for treatment and diagnosis purposes." (PMID 34121877, 2021). "In summary, even though earlier studies have explored the role of CD82 in prostate cancer and other cancer metastasis, our study was the first where we used microarray analysis to observe differential gene expression in prostate cells with and without CD82." (PMID 33298014, 2020). "The functional role exhibited by RUNX3 is very similar to the role CD82 plays in prostate cells, i.e., CD82 reexpression has been shown to inhibit EMT, inhibit migration and invasion and its down-regulation has been correlated with poor prognosis in prostate cancer." (PMID 33298014, 2020). "Therefore, CD82 is likely to have a negative motogenic function without any mitogenic effect on prostate cancer cells." (PMID 27926483, 2017). "Fibronectin induces EMT in prostate cancer cells with no or low levels of CD82, while it promotes MET, the reverse process of EMT, in the cells with high CD82 levels, indicating differential effects of fibronectin on epithelial-mesenchymal plasticity depending on CD82 expression levels." (PMID 27926483, 2017). "Kai I gene (Kangai1/CD82) belong to MSG family, originally identified in Prostate cancer cells, limiting its role not in prostate cancer only but also to various cancers such as lung cancer, pancreatic cancer, gastric cancer, bladder cancer, and breast cancer." (PMID 31759355, 2019). "KAI-1/CD82 is an important member of MSGs; the role of KAI1 has been well explored in prostate cancer, however its role in breast cancer is not fully explored and in fact the results of breast cancer studies are contentious." (PMID 31759355, 2019).
breast cancer (49 papers, 2003 to 2025). A primary or metastatic malignant neoplasm involving the breast. "Preliminary data revealed that palmitoylation-deficient CD82 mutants (C5A/C74A/C83A) increased apoptotic susceptibility in breast cancer cells, although the mechanistic link between CD82 palmitoylation and drug sensitivity remains unexplored." (PMID 41415560, 2025). "This study focuses on the expression and distribution of EGFR and c-Met in breast cancer as well as the related metabolic pathways and molecular mechanisms associated with different CD82 palmitoylation site mutations." (PMID 35538033, 2022). "Altogether, these findings suggest that PPFIA1 could potentially act as in regulating CD82 expression and integrin signalling causing tumour progression and invasion in luminal breast cancer." (PMID 32410585, 2020). "Yang and co-workers further showed in another study that a lower CD82 protein expression was associated with breast malignancy as analyzed by immunohistochemistry in breast tissues from 81 patients (comprising 7 normal tissues, 7 ductal carcinoma in situ and 67 breast cancer tissues)." (PMID 34503296, 2021). "A palmitoylation-deficient CD82 mutant (C5A/C74A/C83A) was generated and expressed in MDA -MB-231 breast cancer cells." (PMID 41415560, 2025). "Lastly, CA displayed promising in vitro potential against cellular factors related to stages of metastasis, with the ability to stimulate CD82 in breast cancer cells and inhibit in vivo angiogenesis." (PMID 38753184, 2024). "The suppressor of KAI1 in breast cancer inhibits the KAI1/CD82 metastasis suppressor gene and is known as metastasis-inducing lncRNA, which is upregulated in TNBC." (PMID 39130753, 2024). "Seventeen ethanolic plant extracts were screened for their effect on cell proliferation (against MDA-MB-231 and MCF-7 breast cancer and Hek293 kidney cells), cell invasion and effect on CD82 expression in metastatic MDA-MB-231 cells." (PMID 38753184, 2024). "Future studies should explore breast cancer xenograft models to assess the extracts’ impact on CD82 expression and angiogenesis in the tumor microenvironment, along with isolating bioactive compounds from the extracts." (PMID 38753184, 2024). "This study screened for plant extracts displaying effects on cell proliferation, invasion, and CD82 expression in breast cancer cells, and in vivo angiogenesis, and further correlated between the biological activities and effect on CD82 expression." (PMID 38753184, 2024). "A study on breast cancer demonstrated that the level of CD82 in serum-derived exosomes was significantly higher in a malignant group than in the healthy control group." (PMID 35757760, 2022). "Breast cancer-associated fibroblast-derived exosomes are enriched in tetraspanins, such as CD63, CD81, and CD82, whereas only CD81 is responsible for the transport of Wnt 11 cargo to exosomes." (PMID 36611951, 2022). "After transfection, the cytoplasmic and membrane proteins of breast cancer MDA-MB-231 cells, with mutations at different palmitoylation sites of CD82, were separated and extracted." (PMID 35538033, 2022). "Studies on the metabolic pathways and mechanisms of CD82 and tumor metastasis-related factors in breast cancer cells will help further understand the mechanism of breast cancer formation and metastasis and provide ideas for more precise targeted therapy." (PMID 35538033, 2022). "They postulated that a redistribution of the CD82 protein via exosomes from breast cancer tissues to blood occurs during breast cancer development." (PMID 34503296, 2021). "The knockdown of CD82 expression in MDA-MB-231 breast cancer cells promoted cell migration and invasion, which was posited to be via the dysregulation of mitogen-activated protein kinase (MAPK) signaling, and the interaction of CD82 with EGFR." (PMID 34503296, 2021). "CD82 is expressed in most cells and its expression is lost early during tumor progression in various tissues including prostate and breast cancers." (PMID 34207462, 2021).
breast cancer (continued). "The next section focuses on the therapeutic value of CD82 in curbing breast cancer metastasis, which is the cancer of interest in this review." (PMID 34503296, 2021). "Recently, a novel lncRNA named SKAI1BC (Suppressor of KAI1 in Breast Carcinoma) has been shown to epigenetically inactivate the anti-oncogenic activity of KAI/CD82 in breast cancer." (PMID 34503296, 2021). "This review explores the prospect of targeting CD82 as an innovative therapeutic approach in precision medicine for breast cancer patients, with the goal of preventing cancer progression and metastasis." (PMID 34503296, 2021). "Liprin-α1 suppresses the expression of the transmembrane metastasis suppressor CD82 in HNSCC and breast cancer cell lines, and the expression of liprin-α1 and CD82 is negatively correlated in clinical breast cancer samples." (PMID 34654889, 2021). "CD82 is known to play a significant anti-metastatic role in multiple cancers, including breast cancer." (PMID 34503296, 2021). "CD82 mRNA expression was also observed to be reduced in breast cancer tissues as compared to normal breast tissue." (PMID 34503296, 2021). "This review will focus on CD82, a metastatic suppressor, and evaluate its potential usage as a therapeutic strategy in overcoming the distant spread of breast cancer cells." (PMID 34503296, 2021). "Such an approach would entail the selection of a subset of breast cancer patients with low levels of CD82, and instituting an appropriate treatment scheme tailored towards restoring the levels of CD82 in this group of patients." (PMID 34503296, 2021). "The metastasis suppressors KAI1 (also known as CD82) has been found to inhibit tumor metastasis in various types of solid cancers, including breast cancer." (PMID 34121877, 2021). "Overexpression of Sulfatase 2 (Sulf 2) was also reported to promote cell migration and invasion with the concomitant downregulation of CD82 expression in MDA-MB-231 breast cancer cells." (PMID 34503296, 2021). "A novel metastasis inducing lncRNA which suppresses the KAI1/CD82 metastasis suppressor gene and is upregulated in TNBC has been reported and named Suppressor of KAI1 in Breast Cancer (SKAI1BC)." (PMID 33572395, 2021). "When we knocked down liprin-α1 in HNSCC and breast cancer cells grown in two-dimensional cell culture, CD82 was located at the vesicle-like structures and showed partial co-localization with caveolin-1." (PMID 30005669, 2018). "Due to our results showing the association between liprin-α1 and CD82, we explored the significance of PPFIA1 amplification in survival of clinical HNSCC and breast cancer patients from The Cancer Genome Atlas (TCGA) data." (PMID 30005669, 2018). "In subsequent studies, the metastasis suppressor function of CD82/KAI1 was demonstrated in many other cancer cell types including breast cancer, melanoma, sarcoma, pancreatic cancer, and hepatocarcinoma cells." (PMID 27926483, 2017). "There is even a synergy in simultaneous reduction of CD9 and CD82 that leads to increased metastatic potential in breast cancer." (PMID 25285080, 2014). "We also showed that decreased KAI1/CD82 gene expression was an indicator of poor prognosis in lung cancer, breast cancer and pancreatic cancer." (PMID 12838318, 2003). "It is interesting to note that Wang and colleagues recently showed that exosomal tetraspanin CD82 was much more abundant in the serum of breast cancer (BC) patients than in healthy controls and that CD82 expression rose sharply as malignant breast cancer progressed." (PMID 40305328, 2025). "Breast cancer metastasis relies on cellular invasion and angiogenesis facilitated by the downregulation of metastatic suppressor proteins like Cluster of Differentiation 82 (CD82)." (PMID 38753184, 2024). "Furthermore, there are no studies which identify the correlation between the anti-invasive effects of plant extracts and the expression of CD82 protein in breast cancer cells." (PMID 38753184, 2024).
breast cancer (continued). "The KAI1 or CD82 gene is a major tumor metastasis suppressor that primarily inhibits cancer cell motility and invasiveness in a wide variety of solid malignant tumors, such as prostate, stomach, colon, hepatocarcinoma, thyroid, pancreas, and breast cancers." (PMID 37700002, 2023). "The results also suggested that the level of CD82 was positively correlated with the malignancy of breast cancer and thus could sensitively serve as a breast cancer marker." (PMID 35757760, 2022). "The effect of CD82 palmitoylation site mutation on the expression, location, and metabolism of EGFR and c-Met in breast cancer cells remains unclear so far." (PMID 35538033, 2022). "Interestingly, it was reported that imatinib up-regulated CD82 gene expression in human MCF-7 breast cancer cells, concomitant with a significant inhibition in cell proliferation." (PMID 34503296, 2021). "The same authors observed an association of CD82-positive metastases with the estrogen receptor (ER)-negative phenotype, implying that CD82 is not a good determinant of cancer progression in this breast cancer subtype." (PMID 34503296, 2021). "In addition, CD82 mRNA expression was observed to be significantly reduced in breast cancer metastases to the brain." (PMID 34503296, 2021). "Proposed precision treatment regimens include current modalities of treating breast cancer, in combination with either clinically approved drugs that could restore the levels of CD82, CD82 peptide mimics or non-coding RNA-based therapeutics." (PMID 34503296, 2021). "This review aims to discuss the role of KAI1/CD82 as a prognosticator in breast cancer." (PMID 34121877, 2021). "CD82 was identified as to be a useful indicator of poor prognosis in breast cancer patients." (PMID 34222462, 2021). "CD82, also known as KAI1, a glycoprotein belonging to the tetraspanin family and an established metastasis suppressor, could potentially be exploited to hinder metastases in breast cancer." (PMID 34503296, 2021). "Likewise, in vitro studies have revealed that CD82 plays an important role in cell adhesion, migration and invasion in breast cancer cells." (PMID 34503296, 2021). "Whether CD82 mimics or non-coding RNA therapeutics will be part of the arsenal in overcoming breast cancer metastasis remains to be further investigated." (PMID 34503296, 2021). "In breast cancer, CD82 was also reported to redistribute from tumour tissues to exosomes." (PMID 31034520, 2019). "Therefore, further isolation of bioactive compounds and pre-clinical testing should be considered for CA and PS to identify the compounds responsible for the stimulation of CD82, and correlating anti-invasive activity, as a novel therapeutic mechanism against breast cancer." (PMID 38753184, 2024). "Hence, expression levels of CD82 measured in exosomes could be useful as a potential biomarker for determining the metastatic potential in breast cancer." (PMID 34503296, 2021). "The metastasis suppressive functions of CD82 have been reported to be abrogated by the splicing of the CD82 gene, where the CD82 spliced variant was observed to enhance cell migration and proliferation, concomitant with the activation of Src kinase in MDA-MB-231 breast cancer cells." (PMID 34503296, 2021). "Hence, CD82 could possibly be a feasible molecular target for impeding metastases in breast cancer patients." (PMID 34503296, 2021). "c-Met inhibition by CD82 could involve mechanisms similar to those observed in breast cancer cells." (PMID 33298014, 2020). "However, the role of HuR-β-catenin axis in breast cancer invasion and metastasis needs to be confirmed, and whether HuR inhibition induced CD82 upregulation is related to β-catenin reduction, remains further studies." (PMID 32332873, 2020).
breast cancer (continued). "Therefore, there may be a redistribution of CD82 from tissue to serum exosomes, which reflects tumorigenesis and progression of breast cancer." (PMID 31355262, 2019). "Regarding breast cancer, astaxanthin increases the activation of metastasis, suppressing mammary serine protease inhibitor, KAI1 (CD82), breast cancer metastasis suppressor 1 and mitogen-activated protein kinase kinase 4 on T47D cells." (PMID 39334719, 2024). "Our work reveals that expression of the metastasis suppressor tetraspanin CD82/KAI1, indicative of good prognosis in breast cancer, is a regulator of cell mechanics in breast epithelial cell lines." (PMID 34207462, 2021). "In this same study, exposure to fulvestrant, a clinically approved ER antagonist was observed to upregulate CD82 expression in ER+ MCF-7 and T-47D breast cancer cells." (PMID 34503296, 2021). "Additionally, knockdown of liprin-α1 protein in breast cancer cells MDA-MB-231 and Hs578T controls cell edge protrusions during invasion and metastasis and is encoded by PPF1A1, which could lead to the upregulation of KAI1/CD82." (PMID 34306081, 2021). "This review focuses on one of these metastasis suppressors, the KAI1 (also known as CD82), and an up-to-date account on its effect on the diagnosis and prognosis of breast cancer patients is presented." (PMID 34121877, 2021). "Our results revealed a unique interplay between liprin-α1 and CD82 transmembrane protein in the invasion of HNSCC and breast cancer cells, thus providing mechanistic details of liprin-α1 function in cancer cell progression." (PMID 30005669, 2018). "On the other hand, KAI1/CD82 expression was demonstrated to be consistently downregulated during the progression of human colon cancer, as well as breast cancer, pancreatic cancer and nonsmall cell lung cancer." (PMID 12838318, 2003). "To date, there are currently no drugs which target the upregulation of the CD82 protein in breast cancer to prevent the initial stages facilitating metastatic progression of the disease." (PMID 38753184, 2024). "Here, we propose a precision oncology-based model of preventing metastases by an appropriate selection of non-metastatic breast cancer patients with low CD82 expression." (PMID 34503296, 2021). "Interestingly, Wang and colleagues recently showed that the level of exosomal tetraspanin CD82 was significantly higher in the serum of BC patients compared to healthy controls, while the expression of CD82 significantly increased with malignant breast cancer progression." (PMID 33803776, 2021). "In a previous study, we investigated the expression level of KAI1 by immunohistochemistry from breast cancer tissue and none-neoplastic breast tissues using anti-CD82 TS82B." (PMID 32986351, 2020). "The transfer of the KAI1/CD82 gene into mammary cancer cells suppresses their metastatic potential but does not affect primary tumor growth." (PMID 23420768, 2013). "Besides, KAI1/CD82 expression in tissues shaded negatively with the level of KAI1/CD82 in exosomes, indicating that the KAI1/CD82 expression was redistributed from tissues to the blood as breast cancer developed and metastasized." (PMID 34306081, 2021). "To date, there have been no reports in the literature on miRNAs that target CD82 in breast cancer." (PMID 34503296, 2021). "However, more in vitro and in vivo experimentation, as well as a larger cohort of breast cancer patients, are required to validate that metastasis in ER-negative tumors is independent of CD82." (PMID 34503296, 2021). "Thus, it may be meaningful to verify if etoposide upregulates CD82 expression in breast cancer patients, for repurposing as a therapeutic agent in treating a subset of non-metastatic breast cancer patients with low CD82 expression." (PMID 34503296, 2021).